CXCR2 (C-X-C motif chemokine receptor 2)
Diseases named in the same sentence as CXCR2 in open-access papers (continued):
Sharing a sentence is not in itself a finding about the gene and the disease.
pancreatic cancer (continued). "Since IL-8 treatment induces myotube atrophy via the receptor CXCR2, we next aimed to determine the extent to which the CXCR2 antagonist, SB225002, could attenuate human pancreatic cancer cell CM-induced atrophy." (PMID 31769424, 2019). "Encouraging results have been reported by recent studies showing that pancreatic carcinoma could be inhibited by controlling several biomarkers such as SMAD4, CXCR2, ABCG2 and Kras." (PMID 28077929, 2017). "Interestingly, previous studies reported that that disrupting myeloid cell recruitment by jointly blocking CXCR2 and CCR2 could enhance anti-tumor immunity and therapeutic responses in pancreatic cancer models." (PMID 38750114, 2024). "CXCR2-expressing CAR-T cells against the integrin αvβ6 can migrate more efficiently towards tumor-conditioned media containing IL-8 and exhibit superior antitumor activity against established αvβ6-expressing ovarian or pancreatic tumor xenografts, with a more favorable toxicity profile." (PMID 38727261, 2024). "Moreover, impaired localization resulting from the absence of CXCR2 and impaired tumor cytotoxicity contributed to NK cell immune evasion in patients with pancreatic cancer." (PMID 38835055, 2024). "Preclinical models demonstrated that IL-8 receptor, CXCR1 or CXCR2, -modified CARs remarkably favored T cell migration and persistence in TME, thereby inducing complete cancer regression and immunologic memory in aggressive tumors such as ovarian, glioblastoma, and pancreatic cancer." (PMID 36168626, 2022). "A number of previous studies have investigated if C-X-C motif chemokine receptor (CXCR) 2 and C-X-C motif chemokine receptor (CXCR) 4 play an important role in tumor proliferation, invasion, angiogenesis, metastasis and migration in numerous types of malignancies, including pancreatic cancer (PC)." (PMID 32867211, 2020). "Interestingly, we found that both pancreatic cancer cells and PSCs expressed IL-8 receptors CXCR1 and CXCR2 implicating the possibility that G9a-increased IL-8 could affect cancer cells and PSCs simultaneously." (PMID 27531902, 2016).
melanoma (95 papers, 2004 to 2025). A malignant, usually aggressive tumor composed of atypical, neoplastic melanocytes. "In the NRas/Ink4a model of melanoma, loss of CXCR2 expression during tumorigenesis also resulted in reduced tumor growth, without a significant reduction in tumor incidence." (PMID 37270599, 2023). "Here, we provide novel mechanistic insight revealing how loss of Cxcr2 expression/activity in melanoma tumor progenitor cells results in reduced tumor burden and creation of an anti-tumor immune microenvironment." (PMID 37270599, 2023). "Genetic loss of Cxcr2 or pharmacological inhibition of CXCR1/CXCR2 during melanoma tumor induction resulted in key changes in gene expression that reduced tumor incidence/growth and increased anti-tumor immunity." (PMID 37270599, 2023). "Pre‐clinical evidence suggests that tumour‐associated CXCR1 and CXCR2 overexpression correlates with increased proliferation and microvessel density and reduced apoptosis in melanoma." (PMID 37170733, 2023). "In contrast, loss of CXCR2 or inhibition of CXCR1/CXCR2 in melanoma progenitor cells is associated with expression of genes associated with inflammation, T cell recruitment, pluripotency, and reduced tumorigenicity." (PMID 37270599, 2023). "CXCR2 activation is associated with cell proliferation, angiogenesis, metastasis and chemoresistance in melanoma, colon, lung and ovarian cancers." (PMID 34038868, 2021). "Elevated levels of CXCR1 or CXCR2 have been associated with increased melanoma cell proliferation and invasion, whereas inhibition of these receptors has been shown to impede melanoma cell growth, movement, and vascularization both in laboratory settings and animal models." (PMID 40124384, 2025). "The CXCL8/CXCR2 axis was also found to associate with metastasis of melanoma." (PMID 34503058, 2021). "CXCR1 and CXCR2 have been linked to melanoma tumor growth and metastasis." (PMID 30873179, 2019). "Clinical studies are ongoing to investigate relationships between anti-PD-1 antibody response and the plasma levels of CXCR2-dependent chemokines as well as genetic inflammasome polymorphisms in advanced melanoma patients undergoing checkpoint inhibitor therapy." (PMID 30400822, 2018). "Additionally, CAR-T cells expressing CXCR1 or CXCR2, which bind IL-8—a chemokine implicated in tumorigenesis within the tumor microenvironment—have demonstrated efficacy in targeting prostate, ovarian, melanoma and colon cancer cells." (PMID 39791742, 2025). "We demonstrate that targeted deletion of Cxcr2 in tyrosinase-expressing melanoma precursor cells concurrent with induction of the BrafV600E transgene and loss of Pten expression or induction of NRasQ61R and loss of Ink4a, resulted in a significant reduction of melanoma burden." (PMID 37270599, 2023). "Promising results have been observed with CXCR2 CAR-T cells against melanoma, CCR2b CAR-T cells against mesothelioma and GD2-CAR-T cells against neuroblastoma." (PMID 39791742, 2025). "SCH‐527123, a small‐molecule antagonist of CXCR1 and CXCR2, was found to significantly inhibit proliferation, migration, and invasion of human melanoma cell lines A375 and M14, while promoting apoptosis." (PMID 40740483, 2025). "CXCL1 expression in malignant melanoma cells is also dependent on CXCL1 itself inducing CXCR2 activation, which results in increased NF-κB activity in a mechanism dependent on Ras and p38 MAPK, which thus increases CXCL1 expression." (PMID 38673949, 2024). "Inhibition of CXCR2 in G-MDSCs augments the efficacy of CD47 blockade in promoting melanoma tumor cell clearance." (PMID 38720108, 2024). "Potential mechanisms by which Cxcr2 affects melanoma tumorigenesis in these murine models were explored using RNAseq, mMCP-counter, ChIPseq, and qRT-PCR; flow cytometry, and reverse phosphoprotein analysis (RPPA)." (PMID 37270599, 2023).
melanoma (continued). "To clarify the concept of an autocrine role for CXCR2 and its ligands in melanoma progenitor cells, we used inducible, autochthonous models of malignant melanoma in mice." (PMID 37270599, 2023). "This work was designed to examine the role of CXCR2 expression during the process of melanoma tumorigenesis." (PMID 37270599, 2023). "By using in vivo zebrafish model, we previously evidenced the role of Bcl-xL in sustaining and inducing melanoma aggressiveness, via an autocrine pathway involving IL-8 and its receptor C-X-C motif chemokine receptor 2 (CXCR2)." (PMID 37488586, 2023). "The overexpression of CXCL8 in melanoma is associated with disease progression, as an increased expression of CXCL8 and CXCR1 and CXCR2 has previously been associated with melanoma transition from a radial (early stage) to vertical (later stage) growth phase." (PMID 37170733, 2023). "In vitro studies on cell lines have confirmed that CXCR2 activation increases proliferation in various types of cancer, including colon cancer, esophageal carcinoma, gastric cancer, malignant melanoma, and ovarian cancer." (PMID 37686093, 2023). "The expression level of miR-449c was increased in myeloid progenitor cells of melanoma-bearing mice in response to activation of C-X-C motif chemokine receptor 2 (CXCR2)." (PMID 37767098, 2023). "It has previously been demonstrated that CXCR1 activation mediates chemotaxis, whereas CXCR2 activation promotes angiogenesis, invasion and migration of human melanoma cells." (PMID 37170733, 2023). "Consistent with this concept, we have shown that the antagonism of CXCR2 upregulates PD-L1 expression and enhances the response of melanoma cells to anti-PD-1." (PMID 37270599, 2023). "To characterize the role of CXCR2 during melanoma tumorigenesis, we generated tamoxifen-inducible tyrosinase-promoter driven BrafV600E/Pten−/−/Cxcr2−/− and NRasQ61R/INK4a−/−/Cxcr2−/− melanoma models." (PMID 37270599, 2023). "Using two distinct modes of triggering the formation of malignant melanoma, we found that tumor onset, growth, and outcome accompanied changes in the tumor microenvironment (TME) and gene expression when Cxcr2 was deleted in melanoma precursor cells." (PMID 37270599, 2023). "Survival analysis comparing patients with high CXCR2 expression (n = 114) to patients with lower CXCR2 expression (n = 107) indicates that CXCR2 expression correlates with decreased overall survival of melanoma patients (p = 0.035)." (PMID 37270599, 2023). "To confirm these results, we also used immunohistochemistry to co-stain for SOX10 (a melanoma marker) and CXCR2." (PMID 37270599, 2023). "While shRNAs have previously been used to knock down CXCR1 and CXCR2 in a human melanoma cell line showing inhibition of tumor growth and microvessel density, these experiments were performed in immune deficient mice and with only one cell line." (PMID 37270599, 2023). "A clinical trial (NCT01740557) was initiated to evaluate the efficacy of T cells transduced with CXCR2 and with nerve growth factor receptor (NGFR), associated with Recombinant Human IL-2 (Aldesleukin) infusion in melanoma." (PMID 35211124, 2022). "Based on the GEPIA analysis 30, high level of CXCL1, CXCL2 and CXCR2 genes indeed often predicted the poor prognosis in melanoma patients." (PMID 35265199, 2022). "This was first performed by Kershaw and colleagues using the chemokine receptor CXCR2 to improve migration towards CXCL1-secreting human melanoma cell lines in 2002." (PMID 36366354, 2022). "A direct tumor-promoting role has been ascribed to CXCL8 by promoting in vivo melanoma and in vitro pancreatic tumor growth via CXCR2." (PMID 34503058, 2021). "The most significant chemokine in angiogenesis in melanoma is CXCL8, which can have paracrine and autocrine effects when it binds to CXCR1 and CXCR2, expressed on melanoma cells and endothelial cells within the TME." (PMID 34830780, 2021).
melanoma (continued). "Using a transgenic model of BRAFV600E melanoma, we found anti-PD-1 immunotherapy to induce the upregulation of several CXCR2-dependent chemokines in primary melanoma tissues." (PMID 34638239, 2021). "In a murine model of melanoma, inhibiting CXCR2 after surgical resection of the primary tumor significantly extended survival and reduced the incidence of distant metastases." (PMID 34944914, 2021). "It signals through the CXCR2/CXCR1 receptors and targeting CXCR2/CXCR1 caused repression of tumour growth in lung and melanoma models." (PMID 34885111, 2021). "When the CXCR1/CXCR2 signalling pathway is blocked, new vessel formation is greatly reduced, and melanoma growth is inhibited." (PMID 34830780, 2021). "CXCR1 and CXCR2-overexpressing tumours show an increased proliferation of melanoma cells and increased microvessel density, with evidence of reduced apoptosis in both cell lines in in vitro and in vivo models." (PMID 34830780, 2021). "For example, significant inhibition of human melanoma tumor growth and lung metastasis with a decrease in melanoma cell proliferation and angiogenesis has been shown in Cxcr2–/– mice compared to WT nude mice." (PMID 34124076, 2021). "Small molecule antagonists targeting CXCR2 inhibit the proliferation, migration, and invasion of melanoma cells, such as SCH-527123." (PMID 33336008, 2020). "This cytokine has been already implicated in promoting tolerance of melanoma cells to BRAF inhibition, and its receptor C-X-C motif chemokine receptor 2 (CXCR2) was suggested as a potential target in melanoma." (PMID 31936151, 2020). "MAGE-A3 TCR transgenic T cells overexpressing CXCR2 exhibited superior tumor infiltration capacity in a xenograft mouse model of human melanoma." (PMID 32570906, 2020). "Three years later, a live mouse study demonstrated that CXCR2 plays a key role in melanoma lung metastasis through a gene knockout model." (PMID 32894090, 2020). "For instance, elevated levels of CXCL8/IL-8 in the melanoma microenvironment can be harnessed by engineering T cells to overexpress the matching chemokine receptor CXCR2." (PMID 32570906, 2020). "In vivo studies in two xenograft tumor models have also shown that melanoma antigen-specific CXCR2-engineered T cells improved tumor migration and antitumor activity in mice bearing MC38/gp100 tumors or CXCL1-expressing tumors." (PMID 33680923, 2020). "It indicates that the expression of CXCL8 and CXCR2 contributes to the aggressive growth and metastasis of human malignant melanoma." (PMID 32894090, 2020). "In contrast, increased serum levels of chemokines CXCL1 and CXCL2 in mice correlated with increasing levels of CXCR2-expressing neutrophils in the blood and enhanced melanoma growth, with tumor growth being reduced by antibody-mediated blocking of CXCR2." (PMID 33105656, 2020). "Previous studies had demonstrated that chemokine interleukin-8 (CXCL8), the ligand of CXCR2, acted as autocrine and/or paracrine growth and proangiogenic factor for melanoma through CXCR2, inducing invasion and migration." (PMID 29599927, 2018). "A vast majority of melanomas express CXCR2, which stimulates metastatic outgrowth, likely due to its ability to bind CXCL8." (PMID 30591657, 2018). "Among these, CXCL1, CXCL2, and CXCL5 can bind to chemokine receptor CXCR2, which is expressed on several melanoma cell lines and mediates signaling to significantly facilitate their growth in vitro and in vivo." (PMID 29541408, 2018). "The inhibition of neutrophil migration by blocking of chemokine receptor CXCR2 or in CXCR2 deficient mice was shown to reduce tumor angiogenesis and growth in B16F10 melanoma and Lewis lung carcinoma mouse models." (PMID 29340117, 2017). "Downregulation of CXCR1 and CXCR2, by interfering siRNA, inhibits melanoma tumor growth and cell invasion; similarly RNAi of GROα suppresses tumor growth in hepatocellular carcinoma." (PMID 29081734, 2017).
melanoma (continued). "It has been reported that the use of CXCR1/CXCR2-specific antibodies in vitro can inhibit melanoma tumor growth." (PMID 28454081, 2017). "Our data emphasize that IL-1β cannot directly induce tolerance to MAPK inhibition in melanoma cells but requires signaling through CXCR2." (PMID 28450382, 2017). "Limited number of reports on targeted inhibition of Gro family chemokines, CXCL8 (IL-8) and their receptors (CXCR1 and CXCR2) in various tumor models including melanomas, suggested a potential applicability of these approaches for tumor growth inhibition." (PMID 28129639, 2017). "We have previously reported anti-tumor and anti-metastatic effects of CXCR2-antagonists in melanoma and colon cancer respectively." (PMID 26771140, 2016). "Recent studies support the role of granulocytic MDSCs to induce EMT in a melanoma model mediated by the chemokine receptor expressed on MDSCs, CXCR2." (PMID 24733360, 2014). "Two high-affinity receptors for CXCL-8, CXCR1 and CXCR2, are differentially expressed on melanoma and endothelial cells." (PMID 23342280, 2012). "The increased expression of CXCR2 has been suggested to promote tumor growth, angiogenesis, and metastasis in head and neck cancer, non-small-cell lung cancer, ovarian cancer, and melanoma." (PMID 22789011, 2012). "Pharmaceutical inhibition of CXCR2 reduced PMN-MDSC attraction by melanoma cells in vitro and genetic deletion of CXCR2 impaired their recruitment to the primary tumor in vivo." (PMID 21980263, 2011). "CXCL8 and CXCR2 were detected via immunostaining in metastatic lesions (e.g., draining LNs) in human malignant melanoma specimens, supporting their contributions to aggressive growth and metastasis." (PMID 24212647, 2011). "Over-expression of CXCR1 and CXCR2 in melanoma cells conferred an aggressive phenotype to melanoma cells based on enhanced proliferation, migration, and tumor growth in mice." (PMID 24212647, 2011). "Previously, we showed that targeting of chemokine receptors, CXCR1 and CXCR2, in malignant melanoma by small-molecule antagonists led to reduced tumour growth, invasion, and angiogenesis." (PMID 21045835, 2010). "CXCR1 and CXCR2 are expressed by melanoma and are involved in melanoma proliferation and metastasis." (PMID 24281094, 2010). "CXCR1- or CXCR2-induced modulation of melanoma cell proliferation and migration was observed to be mediated through the activation of ERK1/2 phosphorylation." (PMID 19401689, 2009). "Having seen the observable differences in tumourigenicity, we next performed in vitro assays to examine the effect of CXCR1 and CXCR2 overexpression on the growth and malignant behaviour of melanoma cells." (PMID 19401689, 2009). "Immunohistochemical analyses showed significantly increased tumour cell proliferation and microvessel density and reduced apoptosis in tumours generated from CXCR1- or CXCR2-overexpressing melanoma cells." (PMID 19401689, 2009). "In this study, we demonstrated the functional significance of CXCR1 and CXCR2 expression in melanoma growth, tumourigenesis, motility and invasion." (PMID 19401689, 2009). "Our results clearly showed a decrease in cell growth of CXCR1 or CXCR2 overexpressing A375P melanoma cells on treatment with the inhibitor." (PMID 19401689, 2009). "In conclusion, our results suggest that CXCR1 and CXCR2 play important roles in the regulation of human melanoma tumourigenesis and progression." (PMID 19401689, 2009). "In this study, we investigate the precise functional role of CXCR1 and CXCR2 in melanoma progression." (PMID 19401689, 2009). "The aggressiveness of malignant melanoma is associated with differential expression of CXCL-8 and its receptors, CXCR1 and CXCR2." (PMID 19401689, 2009). "Together, these studies demonstrate that CXCR1 and CXCR2 play essential role in growth, survival, motility and invasion of human melanoma." (PMID 19401689, 2009).